PRMT9 (protein arginine methyltransferase 9)
Diseases named in the same sentence as PRMT9 in open-access papers:
PRMT9 is named in the same sentence as 29 diseases in open-access papers, as found by Europe PMC text mining. Sharing a sentence is not in itself a finding about the gene and the disease. The quoted sentences say what the papers report.
hepatocellular carcinoma (10 papers, 2021 to 2025). A malignant tumor that arises from hepatocytes. "Their subsequent research found that PRMT9 inhibits ferroptosis to accelerate hepatitis B virus‐associated hepatocellular carcinoma progression by promoting the arginine methylation of heat shock protein 8 (HSPA8)." (PMID 41394407, 2025). "PRMT9, as a factor of significant interest in hepatocellular carcinoma (HCC) research, influences immune cell infiltration in the HCC immune microenvironment through various complex mechanisms." (PMID 41154773, 2025). "In hepatocellular carcinoma, PRMT9 expression activating the Notch pathway and enhancing malignant phenotypes, including increased proliferation." (PMID 41204384, 2025). "In hepatocellular carcinoma and osteosarcoma, PRMT9 has been described as a factor promoting progression." (PMID 41154773, 2025). "In hepatocellular carcinoma, PRMT9 promotes metastasis by activating PI3K/Akt/GSK‐3beta/Snail signaling." (PMID 41394407, 2025). "PRMT9 has also been shown to have increased expression in certain skin cancers, testicular cancers, pancreatic cancers, lymphomas, and hepatocellular carcinoma (HCC)." (PMID 40869229, 2025). "While literature regarding the pathophysiological contributions made by aberrant expression of PRMT9 is scarce, PRMT9 has been demonstrated to promote hepatocellular carcinoma invasion and metastasis." (PMID 33440687, 2021). "PRMT9 can promote the development and progression of hepatocellular carcinoma and osteosarcoma." (PMID 41154773, 2025). "In Hepatocellular carcinoma (HCC), PRMT9 increases its arginine methylation at R76 and R100 by targeting member 8 of the human heat shock homologous protein family A, accelerates the progression of HCC in vivo." (PMID 38911125, 2024).
osteosarcoma (6 papers, 2017 to 2025). A usually aggressive malignant bone-forming mesenchymal neoplasm, predominantly affecting adolescents and young adults. "Another research team found that PRMT9 was abnormally underexpressed in osteosarcoma and could inhibit glycolysis in osteosarcoma cells by increasing the instability of hypoxia inducible factor 1 α (HIF‐1 α)." (PMID 41394407, 2025). "In osteosarcoma studies, PRMT9 was found to act mainly through miRNA." (PMID 41154773, 2025). "PRMT9 expression is shifted by direct binding of miR-543 to its 3ʹ-UTR and increased levels of this miRNA have been associated with downregulation of PRMT9 and osteosarcoma cell growth." (PMID 35087589, 2022). "MiR-543 has been shown to bind to the 3′-UTR of PRMT9, which inhibits PRMT9 expression and leads to reduced PRMT9-driven cell oxidative phosphorylation and increased hypoxia-induced factor-1α (HIF-1α) stability in osteosarcoma cells." (PMID 33404912, 2021).
acute myeloid leukemia (4 papers, 2024 to 2025). Acute myeloid leukemia (AML) is a group of neoplasms arising from precursor cells committed to the myeloid cell-line differentiation. "Acute myeloid leukemia is characterized by high levels of PRMT9, and leukemia is eradicated by inhibiting PRMT9 by reducing the arginine methylation of proteins involved in RNA translation and the DNA damage response." (PMID 41154773, 2025). "PRMT9 has been shown to act as an oncogene in the development of acute myeloid leukemia (AML)." (PMID 40869229, 2025).
leukemia (3 papers, 2024 to 2025). A malignant (clonal) hematologic disorder, involving hematopoietic stem cells and characterized by the presence of primitive or atypical myeloid or lymphoid cells in the bone marrow and the blood. "Rag2−/− or NSGS mice bearing Prmt9 KD transplants survived significantly longer than mice with Prmt9 WT transplants, but succumbed to leukemia within 60 days." (PMID 38413714, 2024). "Notably, mice receiving PRMT9 KD cells exhibited decreased leukemia burden and prolonged survival, compared with control mice." (PMID 38413714, 2024). "After leukemia cell engraftment, we induced Prmt9 KD and monitored leukemia development." (PMID 38413714, 2024). "Notably, elevated PRMT9 protein levels were seen in an LSC-enriched (CD34+CD38−) relative to a leukemia committed progenitor (CD34+CD38+) subset or to either of the normal subsets." (PMID 38413714, 2024). "Notably, PRMT9 levels were higher in leukemia stem cells (LSCs) relative to either normal hematopoietic stem cells (HSCs) or blasts." (PMID 38413714, 2024). "Thus, Prmt9 KD-mediated leukemia elimination effects are comparable in both models." (PMID 38413714, 2024). "Notably, Prmt9 KD remarkably decreased leukemia-initiating cell frequency in both models." (PMID 38413714, 2024). "However, inhibiting PRMT9 in AML can trigger an anti-leukemia immune response by activating the cGAS-STING pathway, suggesting that PRMT9 may play an immunosuppressive role in this context." (PMID 41154773, 2025).
Intellectual disability (2 papers, 2020 to 2024). "Here, by characterizing an intellectual disability associated PRMT9 mutation (G189R) and establishing a Prmt9 conditional knockout (cKO) mouse model, we uncover an important function of PRMT9 in neuronal development." (PMID 38561334, 2024). "Mutations in protein arginine methyltransferase 9 (PRMT9) are linked to intellectual disability." (PMID 38561334, 2024).
lung adenocarcinoma (2 papers, 2024 to 2025). A carcinoma that arises from the lung and is characterized by the presence of malignant glandular epithelial cells. "A case report has demonstrated that the homozygous PRMT9 (c.G40T:p.G14C) mutations is closely associated with the incidence of lung adenocarcinoma." (PMID 38166853, 2024). "Protein arginine methyltransferase 9 (PRMT9) is dysregulated in various malignancies, particularly in lung adenocarcinoma (LUAD)." (PMID 41394407, 2025).
prostate carcinoma (2 papers, 2018 to 2024). A carcinoma that arises from epithelial cells of the prostate gland. "The AR also associates with PRMT9/10 in the prostate cancer cell line, LNCaP, and knockdown of PRMT9/10 suppressed both cellular growth and expression of the prostate specific antigen (PSA)." (PMID 29568320, 2018). "In contrast to the previously observed high expression, PRMT9 levels were found to be significantly decreased in osteosarcoma and prostate cancer." (PMID 38911125, 2024).
viral infection (2 papers, 2022 to 2023). "When a viral infection occurs, PRMT9 is dislodged from mitochondria, which leads to a reduction in baseline MAVS methylation levels." (PMID 38116532, 2023). "The results of the immunoblots analysis are consistent with the confocal microscope images in PM and THP1 cells, suggesting that PRMT9 localized in mitochondria, and the amount of mitochondrial PRMT9 was gradually decreased upon viral infection." (PMID 36028484, 2022). "Upon virus infection, PRMT9 dissociates from the mitochondria, leading to the aggregation and activation of MAVS." (PMID 36028484, 2022). "Notably, PRMT9-mediated suppression of MAVS autoactivation was broken during viral infection." (PMID 36028484, 2022). "Overexpression of PRMT9 notably suppresses IFN-β expression and promotes viral replication, whereas PRMT9 knockdown or knockout yields the inverse effects following viral infection." (PMID 38116532, 2023). "Overexpression of PRMT9 significantly decreased IFN-β expression and facilitated viral replication, whereas knockdown or knockout of PRMT9 had the opposite effects upon viral infection." (PMID 36028484, 2022). "Further, the interaction between endogenous PRMT9 and MAVS was found to be attenuated upon viral infection." (PMID 36028484, 2022).
Anxiety (1 paper, 2024). Intense feelings of nervousness, tension, or panic often arise in response to interpersonal stresses. "Because Prmt9 is broadly expressed in the developing mouse cortex, including the motor cortex, we assessed the locomotor activity and anxiety-related behaviors in Prmt9 cKO and control littermate mice." (PMID 38561334, 2024).
autoimmune disease (1 paper, 2022). A disorder resulting from loss of function or tissue destruction of an organ or multiple organs, arising from humoral or cellular immune responses of the individual to their own tissue constituents. "Hence, we rationalized that PRMT9 could inhibit the autoactivation of MAVS in unstimulated cells, which may be a potential mechanism for a host to avoid autoimmune diseases." (PMID 36028484, 2022).
liver cancer (1 paper, 2023). An epithelial or non-epithelial malignant neoplasm that arises from the liver. "In our previous work, we have reported that PRMT9 plays an important role in the progression of liver cancer." (PMID 37715221, 2023).
lung carcinoma (1 paper, 2025). "In addition, we measured the expression of PRMT9 in normal alveolar epithelial cells and lung cancer cell lines." (PMID 41394407, 2025). "PRMT9 expression was evaluated in paired clinical LUAD specimens and adjacent normal tissues, as well as in normal alveolar epithelial cells versus established lung cancer cell lines." (PMID 41394407, 2025).
lymphoma (1 paper, 2024). A malignant (clonal) proliferation of B- lymphocytes or T- lymphocytes which involves the lymph nodes, bone marrow and/or extranodal sites. "We next investigated cooperation between PRMT9 inhibitor and αPD-1 treatment using an A20 lymphoma syngeneic model." (PMID 38413714, 2024).
prostate tumor (1 paper, 2024). "PRMT9 is decreased in the prostate tumor tissues as compared with non-neoplastic prostate tissues." (PMID 38166853, 2024).
pulmonary fibrosis (1 paper, 2022). Chronic progressive interstitial lung disorder characterized by the replacement of the lung tissue by connective tissue, leading to progressive dyspnea, respiratory failure, or right heart failure. "Further, the results of hematoxylin-and-eosin staining showed that PRMT9 deficiency alleviated inflammatory cell infiltration, tissue edema and pulmonary fibrosis compared with the Prmt9WT mice following VSV infection." (PMID 36028484, 2022).
rhabdomyosarcoma (1 paper, 2022). A rare aggressive malignant mesenchymal neoplasm arising from skeletal muscle. "The expression of PRMT1, CARM1, PRMT5, PRMT7, PRMT8 and PRMT9 were all elevated in rhabdomyosarcoma, CARM1 and its direct interaction with histone acetyltransferase PCAF jointly were also detected to exert an increased expression of myogenin gene and lead to rhabdomyosarcoma cell differentiation." (PMID 35311114, 2022).
tumor (11 papers, 2017 to 2025). "In vivo studies confirmed that PRMT9 suppression inhibited tumor growth, which was associated with decreased expression of RAS, pMek1/2, pErk1/2, and Ki67, alongside enhanced caspase‐3 expression." (PMID 41394407, 2025). "Promoting tumor cell invasion and metastasis: Overexpression of PRMT9 can enhance the invasive and metastatic capabilities of HCC." (PMID 41154773, 2025). "In tumor tissue samples, knockdown of PRMT9 decreased the levels of RAS, pMek1/2, Ki67, and pErk1/2 proteins, while caspase‐3 levels were increased by knockdown of PRMT9." (PMID 41394407, 2025). "Our study also prompts an appraisal of anticancer drugs with consideration of their impact on immune cells within the tumor microenvironment and provides a rationale for further evaluation of PRMT9 inhibition combined with a PD-1/PD-L1 inhibitor against AML." (PMID 38413714, 2024). "Compared to control mice, Prmt9-deficient mice had a slower AML progression, lower tumor burden, decreased splenomegaly and survival advantage." (PMID 38413714, 2024). "Our study demonstrates that tumor elimination induced by Prmt9 deletion relies on type I IFN responses." (PMID 38413714, 2024). "In vivo, hsa_circ_001726 knockdown also reduced PRMT9 expression in lung tissues of orthotopic transplantation tumor mice." (PMID 38166853, 2024). "We also noted that Prmt9 KD mice exhibited increased CD8+ T cells recognizing tumor survivin relative to Prmt9 WT controls." (PMID 38413714, 2024). "Although numerous studies suggesting the involvement of FBXO11 in tumor progression, PRMT9-mediated arginine methylation modifications in tumors have not been studied much, limited by the short time frame of the studies." (PMID 37715221, 2023). "The results showed that tumor volume and weight were significantly diminished in nude mice in response to PRMT9 knockdown." (PMID 37715221, 2023). "We noted that, although the number of samples in GEO is limited, expression of PRMT2, PRMT4-6 and PRMT9 is elevated in tumor samples." (PMID 34360791, 2021). "In vivo studies revealed that knockdown of PRMT9 significantly inhibited tumor growth." (PMID 41394407, 2025). "Notably, Prmt9 levels were more abundant in leukemic cells than other cells; Prmt9 KD decreased tumor cell frequency relative to controls and induced T cell activation." (PMID 38413714, 2024). "Moreover, Prussian Blue staining revealed a heavier accumulation of iron in HCC tumor tissues after PRMT9 knockdown." (PMID 37715221, 2023). "The expression of PRMT1, PRMT3, PRMT4, PRMT5, and PRMT7 was elevated in tumor samples compared to normal tissue, while PRMT2, PRMT8, and PRMT9 were decreased." (PMID 40399547, 2025). "The results showed that the expression of PRMT9, HSPA8, and GPX4 were significantly higher in tumor than that in adjacent tissues." (PMID 37715221, 2023). "PRMT9 knockdown also significantly suppressed FTH1 protein expression and enhanced MDA content in HCC tumor tissues." (PMID 37715221, 2023). "To investigate the role of PRMT in the development of HNSC, we first analyzed the expression levels of PRMT family members (PRMT1-PRMT9) in tumors using TCGA data, and we found that PRMT6 and PRMT9, the other PRMT family members, had significantly elevated expression in tumor tissues." (PMID 38663941, 2024). "Furthermore, the statistical analysis of clinical data indicated that miR-543 expression was positively correlated with several OS clinical characteristics including tumor grade, size, and TNM stage, P < 0.05, whereas the relationship between miR-543 and PRMT9 was inversely in OS." (PMID 27911265, 2017).
cancer (8 papers, 2017 to 2025). A tumor composed of atypical neoplastic, often pleomorphic cells that invade other tissues. "Although PRMT9 has been linked to diverse cancer diseases, the function of PRMT9 in antiviral innate immunity remains unknown." (PMID 36028484, 2022). "WB and IHC studies found that the levels of PRMT9 protein were abnormally high in the cancer tissues." (PMID 41394407, 2025). "The qPCR results showed that the expression levels of PRMT9 mRNA in cancer tissues were significantly higher than those in tissues adjacent to the cancer." (PMID 41394407, 2025). "For instance, targeting PRMT9-mediated arginine methylation inhibits the maintenance of cancer stem cells and enhances antitumor immunity by activating cGAS-mediated IFN-I responses." (PMID 40166469, 2025). "To investigate the effect of PRMT9 expression on LUAD cancer cells, we knocked down PRMT9 expression in A549 and H1568 cells." (PMID 41394407, 2025). "Based on the scRNA-seq results, among the reported relevant immune checkpoint proteins, Prmt9 KD significantly upregulated PD-L1 in cancer cells, although PD-L2 and CTLA-4 were also modestly upregulated." (PMID 38413714, 2024). "On PRMT9 KD, cancer cells accumulate cytosolic dsDNA, providing abundant substrate for cGAS catalysis." (PMID 38413714, 2024). "Indeed, PRMT9 inhibition or expression of XRN2-R946K in AML cells promoted R-loop formation and ATR signaling, which underlies cGAS activation in cancer cells." (PMID 38413714, 2024). "To assess whether cancer-intrinsic PRMT9 inhibition induces immune responses, we used an MA9 AML transplant model." (PMID 38413714, 2024). "We observed elevated PRMT9 protein levels in AML relative to other cancers." (PMID 38413714, 2024). "How does PRMT9 inhibition in cancer cells elicit a distinct response in T cells?" (PMID 38413714, 2024). "Collectively, we showed a biological role for PRMT9 in cancer." (PMID 38413714, 2024). "Furthermore, overexpression of PRMT9 has been linked to poor outcomes in HCC, demonstrating an augmenting effect on the metastatic potential of cancer cells." (PMID 37627211, 2023). "In summary, we found that PRMT9 is highly expressed in LUAD tissue and promotes cancer cell metastasis and proliferation by maintaining activation of the RAS/MAPK signaling pathway." (PMID 41394407, 2025). "PRMT9 was significantly upregulated at both transcriptional and translational levels in LUAD tissues and cancer cell lines compared to normal controls." (PMID 41394407, 2025). "In cancer tissues of GSE25097, the expressions of PRMT2, PRMT3, PRMT4, PRMT5, and PRMT7 were upregulated in cancer tissues, whereas the expressions of PRMT6 and PRMT9 were downregulated." (PMID 37627211, 2023). "Among the target genes predicted by the miRanda, TargetScan and starBase, PRMT9 attracted our attention because its 3ʹ-UTR contains a putative target sequence for miR-543, and PRMT9 is closely involved in cancer cell proliferation." (PMID 27911265, 2017).
infection (1 paper, 2022). The state of being infected such as from the introduction of a foreign agent such as serum, vaccine, antigenic substance or organism. "Compared with wide-type mice, PRMT9 deficient mice were less susceptible to infection with an RNA virus." (PMID 36028484, 2022). "We found that SeV infection could induce MAVS aggregation in macrophages, while PRMT9 deficiency greatly increased the formation of MAVS aggregates in Prmt9CKO macrophages after infection." (PMID 36028484, 2022). "We also reintroduced PRMT9 (WT) and PRMT9 (G260E) into Prmt9CKO macrophages, followed by infection with SeV and VSV." (PMID 36028484, 2022). "Consistent with the observation from the siRNA knockdown or sgRNA knockout of PRMT9, infection of Prmt9CKO peritoneal macrophages with SeV or stimulation with 5’PPP RNA led to a significant increase in the expression of Ifnb1, Ifnα4, and Cxcl10 mRNA compared with that in Prmt9WT macrophages." (PMID 36028484, 2022).
PRMT9 also shares sentences with these, for which no sentence is quoted: alopecia (1 paper); autism (1); breast carcinoma (1); cerebral aneurysm (1); mandibulofacial dysostosis (1); melanoma (1); multiple myeloma (1); myeloid leukemia (1); ovarian carcinoma (1); Parkinson disease (1).